IL6 (interleukin 6)
Diseases named in the same sentence as IL6 in open-access papers (continued):
Sharing a sentence is not in itself a finding about the gene and the disease.
colorectal cancer (continued). "TAM-derived IL-6 drives the crosstalk between MSCs associated with colorectal cancer, enhancing the migration properties of macrophages in TIME, and promoting tumor growth and metastasis through the IL-6/JAK2/STAT3 axis, subsequently activating the Pi3K/AKT/mTOR signaling." (PMID 35884974, 2022). "It was reported that colorectal cancer patients who received blood transfusions for excessive intraoperative blood loss showed exaggerated postoperative systemic induction of interleukin-6, triggering tumor growth factors and resulting in a poor long-term prognosis." (PMID 35377885, 2022). "The IL-6/STAT3 pathway is associated with an advanced stage in colorectal cancer patients." (PMID 32422984, 2020). "The data indicated that IL-6 might be a potential diagnostic biomarker that could be used to separate colorectal cancer patients from healthy subjects, reporting an AUC of 0.82 in a ROC analysis (95% CI 0.75–0.89)." (PMID 30038723, 2018). "Also, risk reduction for colorectal cancer development with aspirin is related only to specific genotypes near the IL-6 genome." (PMID 28573063, 2017). "Moreover, inhibition of IL-6 in patients with IBD not only reduces intestinal inflammation but also decreases the risk of developing colorectal cancer." (PMID 28957373, 2017). "Researchers have observed that serum IL-6 concentration was associated with the progression, histological grade, and bowel wall invasion as well as tumour size and shorter survival periods of colorectal cancer." (PMID 27034885, 2016). "As for colorectal cancer, previous meta-analysis found that while C-reactive protein and interleukin-6 may be associated with risk of colorectal cancer, the few studies on tumor necrosis factor-α and risk of colorectal cancer mainly found null results." (PMID 27608842, 2016). "However, results from epidemiological studies regarding the association of circulating IL-6 concentrations and risk of subsequent colorectal cancer development have been sparse, as only six prospective studies exist." (PMID 26321888, 2015). "In any case, screening for carriers of IL-6 gene variants with high susceptibility to transcriptional dysregulation by IL-1β should be considered for identification of individuals with high-risk for therapy-resistant colorectal cancer." (PMID 18205904, 2008). "In a mouse model of cancer cachexia (ApcMin/+ colorectal cancer model), increased intestinal permeability was observed with cachexia onset; this leakiness was associated with elevated circulating LPS and interleukin (IL)-6 and marked activation of inflammatory pathways." (PMID 40572244, 2025). "Thus, the inhibition of IL6 may not only reduce intestinal inflammation but also decrease the risk of colorectal cancer." (PMID 41209739, 2025). "However, other microbiota studies noted that Alistipes predominate colorectal cancer mucosa compared with healthy controls, may cause elevated IL-6 levels in the blood, and may promote cancer development by inducing cell growth." (PMID 38396998, 2024). "Thus, IL-6 is implicated in both UC and CD as well as in colorectal cancer (CRC)." (PMID 33946346, 2021). "Furthermore, higher DNA methylation in the IL-6 promoter was found in a minor allele (C) at rs1800796; in contrast, the derived C allele at rs1800795 was associated with lower DNA methylation in colorectal cancer tissues and another cancer type in a publicity available data set, Pancan-meQTL." (PMID 34634929, 2021). "Finally, an additional pathway has been linked to IL‐6‐mediated EMT in colorectal cancer cells." (PMID 28599100, 2017). "Survival was negatively correlated with PD-L1, TNF-α, IL-6, and IL-10 in colorectal cancer; 4-1BB, TGF-β1, IL-8, and IL-10 in gastric cancer; and TGF-β1, IL-6, and IL-10 in pancreatic cancer." (PMID 42193466, 2026).
colorectal cancer (continued). "Colorectal cancer (CRC) is a serious worldwide health concern associated with chronic inflammation and dysregulation of numerous signaling pathways, including IL-6/STAT3, NF-κB, COX-2/PGE2, and IL-23/Th17." (PMID 41616596, 2026). "Alistipes promote Colorectal cancer (CRC) through the IL-6/STAT 3 pathway, suggesting its potential as a CRC biomarker." (PMID 40647352, 2025). "Elevated IL-6 expression has been widely reported in various malignancies, including colorectal cancers." (PMID 41267807, 2025). "Another study suggested that a reduction of EMT and invasive/migratory abilities of colorectal cancer cells was observed upon neutralizing IL‐6 and IL‐8." (PMID 40985344, 2025). "A previous study found that multimodal analgesia reduced the inflammatory response in patients with colorectal cancer undergoing radical surgery by lowering the level of the inflammatory marker IL-6." (PMID 40281425, 2025). "In colorectal cancer, high IL-6 levels correlate with poor prognosis, larger tumor lesions, and liver metastasis." (PMID 41476977, 2025). "The previous study has confirmed thrombocytosis accompanying inflammation-related colorectal cancer and highlighted the crucial role of interleukin-6 (IL-6) in this process." (PMID 40535127, 2025). "It has been shown to decrease oxidative stress markers and inflammatory cytokines such as TNF-α, CRF) and IL-6, promoting better postoperative recovery in laparoscopic colorectal cancer resection." (PMID 40951888, 2025). "The elevated levels of IL-6 in serum have been identified as a significant factor in the progression and prognosis of colorectal cancer." (PMID 40141426, 2025). "In colorectal cancer, IL-6/STAT3 signaling drives proliferation and immune evasion, while in breast cancer, TNF-α enhances metastasis and cell migration." (PMID 41311372, 2025). "This study demonstrates that betulin and its synthetic derivatives, EB5 and ECH147, differentially modulate IL-6 expression in colorectal cancer (CRC) and normal colon epithelial cells." (PMID 41256010, 2025). "In contrast, the SW1116 colorectal cancer cells exhibited a significant increase in IL-6 secretion upon treatment with the ECH147 derivative compared to untreated cells (p < 0.001)." (PMID 41256010, 2025). "EGFR activation in myeloid cells increases STAT3 phosphorylation and IL‐6 expression, promoting colorectal cancer cell proliferation." (PMID 40859900, 2025). "Saroor and colleagues indicated that immune cells which produced IL-6 in colorectal cancer induced tumor progression and in the presence of this interleukin, cancer cells produced miR-21 and miR-29b to further induce immune cell IL6 production." (PMID 41476448, 2025). "A meta-analysis comparing open and laparoscopic colorectal cancer surgery revealed a linear correlation between inflammatory factors, such as interleukin-6(IL-6), IL-1β, tumor necrosis factor-α (TNF-α) levels, neopterin immune index, and POFS." (PMID 40529134, 2025). "Wei et al17 found a similar increase in blood levels of TNF-α, IL-1β, and IL-6 in a rat model of colorectal cancer." (PMID 40241344, 2025). "As a result, elevated IL-6 levels contribute to enhanced tumor invasiveness and metastatic potential in colorectal cancer patients." (PMID 40141426, 2025). "The presence of CEA in colorectal cancer has been demonstrated to stimulate the secretion of IL-6 by Kupffer cells." (PMID 41007818, 2025). "Anthocyanins, particularly cyanidin‐3‐O‐glucoside, suppress inflammation and production of pro‐inflammatory cytokines (COX‐2, TNF‐α, and IL‐6) in colorectal cancer and hepatocellular carcinoma." (PMID 40321606, 2025). "Additional studies have reported that inflammatory markers such as IL-1β, IL-6, and TNF-α are strongly associated with F. nucleatum infection and are more highly expressed in colorectal cancers harboring this bacterium." (PMID 41267807, 2025).
colorectal cancer (continued). "IL-6 likewise increases lactate production in rat hepatocytes, and human colorectal cancer, skeletal muscle cells, as well as in ARPE-19 cells." (PMID 39433211, 2025). "PRRX1 upregulation promotes proliferation, stemness, and chemoresistance in colorectal cancer cells by activating the interleukin-6 (IL-6)/JAK2/STAT3 axis, with IL-6 inhibition reversing its effects on stemness and chemoresistance." (PMID 40860778, 2025). "IL-6 further supports tumor growth through the activation of STAT3, a transcription factor implicated in cancer cell proliferation and metastasis in colorectal cancer cells." (PMID 40143078, 2025). "In colorectal carcinoma, inflammatory cytokines like IL-6 shape the tumor microenvironment, driving cell proliferation, angiogenesis, invasion, metastasis, and therapy resistance." (PMID 41515404, 2025). "In fact, there is clear evidence of a substantial relationship between IL-6, colorectal cancer, and the clinical activity." (PMID 39911672, 2024). "Thrombocytosis has been linked to colorectal cancer (CRC) and elevated levels of interleukin-6 (IL-6)." (PMID 38339232, 2024). "A study involving colorectal cancer patients indicates that IL-6 induces immunosuppression, upregulates PD-L1 levels, and promotes tumor progression." (PMID 39690423, 2024). "There have been studies reporting the alterations of serum IL-6 levels related to tumor characteristics of colorectal cancer." (PMID 38978990, 2024). "For example, network pharmacology prediction and molecular docking of active ingredients in Salvia miltiorrhiza have been performed, and SRC, IL6, and INS were found to be associated with colorectal cancer." (PMID 39689118, 2024). "Colorectal cancer patients with elevated DNAm levels of inflammatory factors, specifically interleukin‐6 (IL‐6), in their visceral AT (VAT) are at an increased risk of developing colorectal cancer." (PMID 38405061, 2024). "While IL6/IL8-JAK2 signaling was reported to induce BRD4 activation in colorectal cancer, leading to chromatin remodeling and resistance to BETi treatment." (PMID 38320998, 2024). "MTERF3 plays an oncogenic role in colorectal cancer development by upregulating interleukin 6 and interleukin 11 to promote colorectal cancer cell growth and enhance radiotherapy resistance." (PMID 38589371, 2024). "Colorectal cancer conditional macrophages increase the chemical resistance of colorectal cancer and reduce drug‐induced cell apoptosis by secreting IL6, which can be blocked by neutralizing anti‐IL6 antibodies." (PMID 38961677, 2024). "Tissue expression of IL-6 in colorectal cancer correlated with lymph node metastasis, venous invasion, and an advanced stage and was a poor prognosis predictor." (PMID 39518029, 2024). "Mesenchymal stem cells derived from human CRCs facilitate colorectal cancer progression via the IL-6/JAK2/STAT3 signaling pathway." (PMID 38673975, 2024). "Our study indicates the need for a prospective study enrolling large numbers of colorectal cancer patients who are willing to have IL-6 gene analysis and cytokine analysis during the treatment of tumor resection." (PMID 38978990, 2024). "It has been shown in human colorectal cancer cell lines, specifically in HT29 carrying the full-length (FL) allele and SW480 harboring the deletion (Δ) allele, that treatment with IL-6 induces the relocation of the MSH3 protein." (PMID 39199686, 2024). "PBMC cultures are a sensitive method to detect an enhanced production of IL-6, also in patients with localized disease, such as preoperative colorectal cancer or radically resected stage III melanoma." (PMID 39518029, 2024). "The limited metabolic influence of IL-6 on the RPE is surprising given that IL-6 treatment has been shown to promote both glucose uptake and lactate efflux in skeletal muscle cells, adipocytes, and colorectal cancer cells." (PMID 38567515, 2024).
colorectal cancer (continued). "IL-6 increases glucose uptake and lactate production in adipocytes, skeletal muscle, and colorectal cancer cells, increasing a host of glycolytic genes in the latter." (PMID 38567515, 2024). "This work supports the rationale that targeting gp130-dependent STAT3 signalling via the dual inhibition of IL-6 and IL-11 is a novel colorectal cancer treatment opportunity." (PMID 38600086, 2024). "Alistipes were increased in fecal samples from patients with advanced stage colorectal cancer, and Alistipes finegoldii was shown to promote colorectal cancer through activation of the IL6/STAT 3 pathway." (PMID 38934090, 2024). "Human colorectal cancer-derived MSCs enhanced the growth and metastasis of colorectal cancer cells in vitro and in vivo via the IL-6/JAK2/STAT3 signaling pathway." (PMID 38951845, 2024). "We identified the presence of an intact gp130 signalling cascade in tumour organoids obtained from colorectal cancer patients by evaluating IL-6 and IL-11-dependent phosphorylation of STAT3." (PMID 38600086, 2024). "Research indicates that IL-6 signaling controls intestinal epithelial cell survival and proliferation and is crucial to the etiology of colorectal cancer and IBD." (PMID 39911672, 2024). "As a multifunctional cytokine regulated by NF-κB, IL-6 is a key tumor promoter during early colorectal cancer development." (PMID 38540292, 2024). "Extensive literatures have demonstrated that Alistipes promotes the development of colorectal cancer by activating the IL-6/STAT3 signaling pathway." (PMID 38721274, 2024). "Chronic inflammation is closely linked to advanced stages of colorectal cancer and metastasis, being associated with elevated inflammatory markers such as C-reactive protein (CRP) and IL-6." (PMID 39682667, 2024). "Our observations demonstrate that dual targeting of IL-6 and IL-11 signalling represents a promising treatment strategy for colorectal cancer." (PMID 38600086, 2024). "The report showed TAM-secreted IL-6-induced chemoresistance by activating the IL-6R/STAT3/miR-204 pathway in colorectal cancer cells." (PMID 39247822, 2024). "The impact of the systemic exposure to IL-6IF was further demonstrated by analyzing the correlation between autoantibodies to this structure and the serum concentration of IL-6 in colorectal cancer patients." (PMID 39518029, 2024). "Excessive STAT3 signalling via gp130, the shared receptor subunit for IL-6 and IL-11, contributes to disease progression and poor survival outcomes in patients with colorectal cancer." (PMID 38600086, 2024). "Increased activity of IL-6 and STAT3 is associated with a poor prognosis in several types of cancer, including colorectal cancer." (PMID 39061221, 2024). "Studies have reported that laparoscopic surgery for colorectal cancer, relative to open abdominal surgery, reduces the increase in serum IL-6 levels after surgery." (PMID 38978990, 2024). "Our study is the first to demonstrate that abdominal wound length influences postoperative IL-6 levels and recovery of flatus passage after colorectal cancer resection." (PMID 38978990, 2024). "It is well‐established that both STAT3 and interleukin‐6 IL‐6 are commonly found in the tumour microenvironment of human and murine colorectal cancer, correlating with reduced survival rates and increased recurrence risks." (PMID 39495702, 2024). "The secretion of interleukin-6 (IL-6) from MSCs increases the secretion of endothelin-1 (ET-1) in colorectal cancer cells, which activates Akt and ERK in endothelial cells, thus enhancing their capacities for vessel formation." (PMID 36824409, 2023). "Experimental models of colorectal cancer have shown that platelet sequestration in the spleen occurs prior to the elevation of the inflammatory cytokine interleukin-6 (IL-6)." (PMID 37701438, 2023). "In the present study, we investigated the regulatory role of IL-6 signaling in colorectal cancer EMT using HCT116 human colorectal cancer cells." (PMID 37047623, 2023).
colorectal cancer (continued). "In animal models and patients, IL-6 is a key inflammatory mediator in the development and progression of colorectal cancer." (PMID 37639070, 2023). "Lewis antigens can bind with DC-SIGN and induce the secretion of inflammatory cytokine secretions (e.g., IL-6 and IL-10) which can promote the establish of a tolerogenic microenvironment for colorectal cancer." (PMID 38090489, 2023). "Published data revealed that high IL-6 levels can be an independent biomarker for a bad prognosis in patients with gastrointestinal cancer, while the results for colorectal cancer were controversial." (PMID 37762967, 2023). "The level of IL-6 secretion was higher in GC cell lines than in colorectal cancer cell lines, and this difference was statistically significant." (PMID 37240178, 2023). "The role of IL6 in promoting cellular proliferation in various types of cancer, such as breast, lung, and colorectal cancer, has been well reported." (PMID 37792745, 2023). "In patients with colorectal cancer, authors reported increasing trends of IL-6 and CRP across stratified levels of deficit accumulation frailty (geriatric assessment domains) ranging from fit to frail." (PMID 37213604, 2023). "IL6 expression is significantly increased in tumor cells and IL6 is used as a marker of advanced colorectal cancer." (PMID 37895197, 2023). "Interleukin-6 stimulated aerobic glycolysis by regulating PFKFB3 at the early stages of colorectal cancer." (PMID 38098990, 2023). "Binding of DC-SIGN with colorectal cancer cell glycosylated antigen promote the secretions of IL-6 and IL-10, and induce an immune tolerogenic microenvironment." (PMID 38090489, 2023). "Human mesenchymal stem cells derived from colorectal cancer have been shown to promote the progression of colorectal cancer through the IL-6/JAK2/STAT3 signaling pathway." (PMID 37958803, 2023). "Our preliminary studies also showed that IL-6 causes E-cadherin reduction and increases protein levels of twist, vimentin, snail, slug and α-SMA in HT-29 colorectal cancer cells." (PMID 37047623, 2023). "In colorectal cancer, IL-6 induced autophagy through the activation of BECN1 and promoted chemotherapy resistance." (PMID 37627167, 2023). "CAFs enhance ovarian cancer invasion and metastasis through DDR2-regulated periostin 27 and promote colorectal cancer metastasis through IL-6-mediated LRG1 upregulation." (PMID 37056933, 2023). "To gain a deeper insight into IL6 expression level in colorectal cancer cells, we analyzed a scRNA-seq dataset collected from a colorectal patient available publicly using the GEO repository (ID: GSE222300) through the use of a Seurat pipeline." (PMID 37185750, 2023). "IL-6 serum levels are elevated in cancer patients, particularly in the advanced stages of malignancies, including colorectal cancer." (PMID 38098074, 2023). "Chen Wei groups suggest that Stattic reduces the STAT3 phosphorylation and total STAT3 level in IL-6-stimulated HCT116 colorectal cancer cells." (PMID 37821959, 2023). "In colorectal cancer patients, it has been previously reported that IL-8 levels rise after surgery, concomitant with the rapid IL-6 surge." (PMID 38067195, 2023). "As evidenced in colorectal cancer, colorectal cancer cells secreted IL‐6, and stimulated platelet production by increasing thrombopoietin secretion." (PMID 37807972, 2023). "The effect of IL-6 on proliferation, metastasis, and tumor immune evasion of colorectal cancer has been demonstrated in recent years." (PMID 36823670, 2023). "In Caco-2, a cell line of human colorectal cancer, C. botulinum type A 62A MVs induced the highest expression levels of IL6, IL8, and CCL2, while C. scindens VPI12708 MVs induced the lowest." (PMID 35185840, 2022). "It has been found that activation of autophagy via IL-6/JAK2/beclin 1 pathway in colorectal cancer in turn facilitates IL-6 secretion by secretory autophagy to promote tumor development and chemotherapy resistance (Center)." (PMID 35927755, 2022).